H2AB3 (H2A.B variant histone 3)
Description:
Atypical histone H2A which can replace conventional H2A in some nucleosomes and is associated with active transcription and mRNA processing. Nucleosomes wrap and compact DNA into chromatin, limiting DNA accessibility to the cellular machineries which require DNA as a template. Histones thereby play a central role in transcription regulation, DNA repair, DNA replication and chromosomal stability. Nucleosomes containing this histone are less rigid and organize less DNA than canonical nucleosomes in vivo. They are enriched in actively transcribed genes and associate with the elongating form of RNA polymerase. They associate with spliceosome components and are required for mRNA splicing. May participate in spermatogenesis.
Synonyms: H2A.Bbd; H2ABBD; H2AFB; H2AFB3; H2A.B.1
Tractability: No criterion of Open Targets' tractability assessment is met for any kind of drug.
Gene: Protein-coding gene on chromosome X (155,459,415 to 155,460,005, reverse strand). Ensembl gene ENSG00000277745.
Subcellular location: Nucleus; Chromosome
Gene Ontology:
Molecular function: protein binding; structural constituent of chromatin; DNA binding; protein heterodimerization activity
Biological process: mRNA processing; nucleosome assembly; heterochromatin formation
Cellular component: chromosome; euchromatin; nucleosome; nucleus
Homologues: Orthologues: chimpanzee H2AB3 (97% identical), macaque H2AB1 (88% identical), macaque H2AB2 (88% identical), mouse H2ab3 (57% identical), rat H2ab3 (57% identical), mouse H2ab1 (56% identical), mouse H2ab2 (50% identical), Drosophila melanogaster His2A:CG31618 (43% identical), Drosophila melanogaster His2A:CG33808 (43% identical), Drosophila melanogaster His2A:CG33814 (43% identical), Drosophila melanogaster His2A:CG33817 (43% identical), Drosophila melanogaster His2A:CG33820 (43% identical), and 15 more. Paralogues in human: H2AB2 (100% identical), H2AB1 (99% identical), H2AC21 (45% identical), H2AL1Q (45% identical), H2AX (45% identical), H2AC6 (44% identical), H2AJ (44% identical), H2AC11 (43% identical), H2AC12 (43% identical), H2AC13 (43% identical), H2AC14 (43% identical), H2AC15 (43% identical), and 15 more.